LIN52 (lin-52 DREAM MuvB core complex component)
Synonyms: C14orf46; c14_5549
Gene: Protein-coding gene on chromosome 14 (74,084,956 to 74,201,493, forward strand). Ensembl gene ENSG00000205659.
Subcellular location (Human Protein Atlas): Nuclear speckles
Pathways (Reactome):
Cell Cycle: Cyclin A:Cdk2-associated events at S phase entry; Cyclin E associated events during G1/S transition; G0 and Early G1; G1/S-Specific Transcription; Polo-like kinase mediated events; Transcription of E2F targets under negative control by DREAM complex; Transcription of E2F targets under negative control by p107 (RBL1) and p130 (RBL2) in complex with HDAC1
Genetic constraint (gnomAD): Loss-of-function variants: 3 observed, 3.56 expected, observed/expected ratio (o/e) 0.84, 90% interval 0.37 to 1.79. That is too few expected variants to judge how well the gene tolerates losing a copy. Missense variants: 25 observed, 38.63 expected, observed/expected ratio (o/e) 0.65, 90% interval 0.47 to 0.9. Synonymous variants: 15 observed, 15.85 expected, observed/expected ratio (o/e) 0.95, 90% interval 0.63 to 1.46.
Homologues: Orthologues: dog LIN52 (100% identical), macaque LIN52 (100% identical), mouse Lin52 (100% identical), pig LIN52 (99% identical), tropical clawed frog lin52 (91% identical), rabbit LIN52 (84% identical), zebrafish lin52 (84% identical), rat Lin52 (83% identical), guinea pig LIN52 (75% identical), chimpanzee LIN52 (60% identical), Drosophila melanogaster lin-52 (35% identical), Caenorhabditis elegans lin-52 (28% identical).
Diseases named in the same sentence as LIN52 in open-access papers:
LIN52 is named in the same sentence as 4 diseases in open-access papers, as found by Europe PMC text mining. Sharing a sentence is not in itself a finding about the gene and the disease. The quoted sentences say what the papers report.
cervical cancer (1 paper, 2021). A primary or metastatic malignant neoplasm involving the cervix. "To determine whether LIN52-S20C can restore DREAM in HPV-positive cancer cells, we stably expressed WT-LIN52 or LIN52-S20C in human cervical cancer cell lines HeLa (HPV18) and SiHa (HPV16)." (PMID 33513914, 2021).
embryonal carcinoma (1 paper, 2011). A non-seminomatous malignant germ cell tumor characterized by the presence of large germ cells with abundant cytoplasm resembling epithelial cells, geographic necrosis, high mitotic activity, and pseudoglandular and pseudopapillary structures formation. "In mouse embryonal carcinoma cells knock-down of lin-9 or lin-54 resulted in significant cell cycle defects, while knock down of lin-37 or lin-52 had no such effects." (PMID 21570388, 2011).
cancer (3 papers, 2021 to 2022). A tumor composed of atypical neoplastic, often pleomorphic cells that invade other tissues. "The expression levels of RBL2 and LIN52 were significantly downregulated in numerous cancers." (PMID 35664326, 2022). "Against this background, DYRK1A is well known to phosphorylate Ser28 in LIN52, an event that converts the proliferative MMB configuration to the repressive DREAM complex, thereby inducing cell cycle arrest or quiescence in many cancer cell types." (PMID 35700053, 2022).
LIN52 also shares sentences with these, for which no sentence is quoted: developmental delay (1 paper).